TPD52 (tumor protein D52)
Diseases named in the same sentence as TPD52 in open-access papers (continued):
Sharing a sentence is not in itself a finding about the gene and the disease.
bladder cancer (1 paper, 2024). "To further elucidate the molecular functions and underlying mechanisms of TPD52 in cancer, we immunoprecipitated exogenous TPD52 from T24 human bladder cancer cells and identified potential interacting proteins by mass spectrometry (MS)." (PMID 39401430, 2024). "The xenograft tumor experiments confirmed that depletion of TPD52 conferred resistance to Bortezomib treatment in bladder cancer." (PMID 39401430, 2024). "Analysis of tissue chips showed that TPD52 was downregulated in human bladder cancer tissues compared with adjacent normal tissues." (PMID 39401430, 2024). "In summary, these results support the idea that Cdc20 depletion endows bladder cancer cells with sensitivity to ER stress‐induced cellular apoptosis mainly via the reduced degradation of TPD52." (PMID 39401430, 2024). "In turn, accumulation of Golgi TPD52 in bladder cancer cells appears to directly result in the cleavage of ATF6." (PMID 39401430, 2024). "Although TPD52 has been generally considered as an oncogene, TPD52 is identified as a novel tumor suppressor in bladder cancer." (PMID 39401430, 2024). "Consistent with our observations, expression of TPD52 was positively correlated with activation of the unfolded protein response (UPR) in the TCGA cohorts of patients with bladder cancer (BCa) or skin cutaneous melanoma (SKCM)." (PMID 39401430, 2024). "To explore TPD52‐associated biological processes, we applied gene set enrichment analysis (GSEA) in the TCGA bladder cancer cohort." (PMID 39401430, 2024). "Compared with that in adjacent tissues, TPD52 expression was downregulated in bladder cancer tissues." (PMID 39401430, 2024). "Here, we demonstrated that TPD52 acts as a tumor suppressor in bladder cancer." (PMID 39401430, 2024). "To further evaluate the clinical correlation between Cdc20 and TPD52, we performed immunohistochemical (IHC) staining in bladder cancer patient samples and found a negative correlation (Rho = ‐0.1928, P = 0.0206) between the two proteins." (PMID 39401430, 2024). "As the expression and role of TPD52 in bladder cancer have not been previously reported, we first evaluated the expression of TPD52 in bladder cancer tissue microarrays." (PMID 39401430, 2024).
brain cancer (1 paper, 2022). A primary or metastatic malignant neoplasm affecting the brain. "The outcomes of the current study highlighted the diagnostic potential of co-expression of KLF14, PKCε, TPD52 and miR-124 in brain cancer." (PMID 35577881, 2022). "Furthermore, TPD52 expression increased with cancer grade and was also found to be associated with brain cancer primary metastasis." (PMID 35577881, 2022). "In metastatic and high-grade brain cancer, TPD52 and PKCε expression were up-regulated and KLF14 and miR-124 expression were down-regulated." (PMID 35577881, 2022). "Few studies have been conducted that report on the expression of TPD52, miR-124, and PKCε genes in brain cancer." (PMID 35577881, 2022). "TPD52 and PKCε were upregulated in brain cancer by 2.5- and 1.6-fold, respectively, whereas, KLF14 and miR-124 were downregulated in brain cancer." (PMID 35577881, 2022). "The study aimed to investigate the possible relation of KLF14, TPD52, miR-124, and PKCε in the development and progression of brain cancer and space occupying lesion (SOL) of the brain." (PMID 35577881, 2022). "Gene expression analysis of the brain cancer samples by qRT-PCR revealed that there was 2.5-fold higher expression of TPD52 in blood of brain cancer patients as compared to healthy controls (P = 0.0015)." (PMID 35577881, 2022). "Additionally, TPD52 expression was found to be lower in brain SOL than brain cancer but higher compared to healthy control." (PMID 35577881, 2022). "Therefore, the main aim of this study was to investigate the gene expression levels and possible correlation between PKCε, TPD52, miR-124 and KLF14 to improve understanding of their contribution in the development of brain cancer and neoplasm lesions." (PMID 35577881, 2022).
clear cell carcinoma (1 paper, 2010). "High-level TPD52 staining was more frequent and TPD52 SPCs were significantly elevated in clear cell carcinomas relative to endometrioid carcinomas." (PMID 20846453, 2010). "The present study identified high TPD52 staining as particularly characteristic of clear cell carcinomas, as this was detected in all cases examined." (PMID 20846453, 2010). "Frequent high-level TPD52 expression in clear cell carcinoma is consistent with the results of array-based comparative genomic hybridisation analyses of ovarian clear cell carcinoma cell lines, where increased TPD52 copy number was noted in 6/12 cell lines examined." (PMID 20846453, 2010). "In contrast, high-level TPD52 staining was most frequent in clear cell carcinomas (8/8, 100%), followed by mucinous (8/10, 80%) serous (115/167, 69%), and endometrioid carcinomas (9/19, 47%), with clear cell carcinomas also displaying the highest median TPD52 SPC." (PMID 20846453, 2010).
cystadenoma (1 paper, 2010). A benign or borderline cystic epithelial neoplasm arising from the glandular epithelium. "Comparisons of MAL2 and TPD52 expression were also made in a smaller cohort of mucinous carcinomas, borderline tumours and cystadenomas." (PMID 20846453, 2010).
endometrioid tumor (1 paper, 2016). A benign, borderline, or malignant epithelial tumor of the female reproductive system characterized by the presence of glands and/or cysts lined by neoplastic cells that resemble endometrial cells. "Corresponding with our study, a recent microarray analysis identified TPD52 over-expression as being associated with improved progression-free survival and overall survival in patients with serous and endometrioid tumors." (PMID 26575170, 2016).
gallbladder cancer (1 paper, 2024). "A comparative analysis of differential proteomic data revealed 7 hypermethylated or down-regulated genes (e.g., FBN1, LPP, SOD3) and 61 hypomethylated or up-regulated genes (e.g., HBE1, SNRPF, TPD52), which contributed to the early diagnosis of gallbladder cancer." (PMID 38427106, 2024).
glioblastoma (1 paper, 2022). The most malignant astrocytic tumor (WHO grade IV). "However, TPD52 expression was lower comparative to glioblastomas, and oligodendrogliomas but significantly up-regulated relative to healthy control." (PMID 35577881, 2022).
liver cancer (1 paper, 2016). An epithelial or non-epithelial malignant neoplasm that arises from the liver. "Little is known about TPD52 expression in liver cancer, we observed its upregulation in HCC but without good enough diagnostic value (AUCs = 0.674)." (PMID 26883192, 2016).
lung squamous cell carcinoma (1 paper, 2017). "TPD52 overexpression was found in lung squamous cell carcinoma (SCC), and TPD52 silencing inhibited migration and invation in lung SCC cells." (PMID 28562687, 2017).
malignant epithelial ovarian tumours (1 paper, 2010). "Immunohistochemical analyses of MAL2 and TPD52 expression were performed using tissue microarray sections including benign, borderline and malignant epithelial ovarian tumours." (PMID 20846453, 2010).
meningioma (1 paper, 2017). A generally slow growing tumor attached to the dura mater. "Further, we used immunoblotting for validation of protein levels of SELENBP1 and TPD52 in MG1 and MG2, which exhibited an upregulation from Grade I to II of meningioma." (PMID 28938569, 2017).
metastatic cancers (1 paper, 2023). A carcinoma which has spread from the original site of growth to another anatomic site. "Furthermore, TPD52 and miR-223 expression were upregulated in the early stages of cancer and non-metastatic cancers." (PMID 37833790, 2023).
mucinous carcinoma (1 paper, 2010). "While high-level MAL2 and TPD52 staining were both frequent in mucinous carcinoma, and apparently increased stepwise from benign to borderline to carcinoma, this was not confirmed by comparisons of both visually and digitally-scored staining values." (PMID 20846453, 2010).
pediatric cancers (1 paper, 2019). "TPD52 is an oncogene overexpressed in various cancers, including breast, prostate, lung, gastric, ovarian and pediatric cancers." (PMID 31649118, 2019).
prostate tumor (1 paper, 2021). "In addition, some genes, including Tumor Protein D52 (TPD52), which is an oncogene, showed hypomethylation in multiple CpG sites in prostate tumor tissues." (PMID 35053153, 2021).
small cell lung carcinoma (1 paper, 2023). Small cell lung cancer (SCLC) is a highly aggressive malignant neoplasm, accounting for 10-15% of lung cancer cases, characterized byrapid growth, and early metastasis. "Bioinformatic analysis results show that TCONS_00020615 is involved in small cell lung cancer possibly through the TCONS_00020615–hsa-miR-26b-5p–TPD52 pathway." (PMID 37098483, 2023).
cancer (73 papers, 2005 to 2026). A tumor composed of atypical neoplastic, often pleomorphic cells that invade other tissues. "Originally identified as a tumour‐associated antigen, TPD52 has drawn attention in cancer research due to its potential role in the development and progression of several malignancies, including BRCA." (PMID 39757112, 2025). "Tumor protein D52 (TPD52) is a cancer-associated protein overexpressed in many cancers, including breast, lung, prostate, ovarian, and pancreatic." (PMID 39355533, 2024). "The elevated expression level of TPD52 has been associated with a variety of human carcinomas such as ovarian carcinoma, prostate carcinoma, and breast carcinoma." (PMID 35087592, 2022). "Aberrant expression of TPD52 (encoding TPD52) has been reported in a wide range of cancers, including BrCa, and several tumor‐suppressive miRNA have been reported to be involved in regulating the expression of these genes." (PMID 31755218, 2020). "A plenty of studies showed that TPD52 was overexpressed in some human cancers and in association with carcinoma metastasis." (PMID 28562687, 2017). "Surprisingly, MALDI-TOF MS revealed the presence of peptides pertaining to TPD52, a secreted coiled-coil motif-bearing cancer-associated protein implicated in endosomal trafficking and in secretion via membrane-bound vesicles." (PMID 21359144, 2011). "Our studies provided new insights into TPD52‐associated cancer etiology." (PMID 35666017, 2023). "In lung squamous cell carcinoma, TPD52 is predisposed to promote cancer cell aggressiveness." (PMID 37564195, 2023). "In order to further understand the clinical significance of MAL2, we selected the top three hub genes (MAL2, CDH1, and TPD52) from the GGI network to analyze their potential roles in drug susceptibility in OC according to the Cancer Therapeutics Response Portal (CTRP)." (PMID 35111745, 2021). "However, TPD52 gene showed overexpression and copy number increases in multiple human cancers and its exogenous expression was associated with the increased anchorage-independent growth and cell proliferation, and metastasis in vivo in immunocompetent hosts." (PMID 28562687, 2017). "Overall, these results indicate that the pIs of p38 and p28 are compatible with their presumed localization in endosomes/MVBs, that both are underglycosylated, and that p28 interacts with the cancer-associated protein TPD52, implicated in endosomal trafficking and secretion via vesicles." (PMID 21359144, 2011). "At present, current evidence indicates that TPD52-targeted vaccines elicit antitumor immunity, positioning them as promising immunotherapeutic targets for cancer intervention." (PMID 40973691, 2025). "As a result, the The Cancer Immunome Database (TCIA) database was used to examine the IPS scores of the various TPD52 and TPD52L2 expression groups." (PMID 40973691, 2025). "MiR-hsa-125b-5p affects cell proliferation, migration, and invasion by targeting multiple tumor suppressor genes such as CD147 and TPD52, and it participates in cancer progression by targeting STAT3, BMPR1B, VEGFA, SphK1, CDKN2A, and Sema4D." (PMID 41361055, 2025). "Utilizing The Cancer Genome Atlas (TCGA), Gene Expression Omnibus (GEO), and tissue microarray datasets, we analyzed TPD52/TPD52L2 expression patterns in patients with GC." (PMID 40973691, 2025). "We found that treatment with Cdc20 inhibitors, such as apcin and Taxol, significantly reduced TPD52 polyubiquitination and degradation and proved to have an excellent synergistic effect with tunicamycin in cancer treatment." (PMID 39401430, 2024). "Inactivation of Cdc20 sensitized cancer cells to treatment with the ER stress inducer in a TPD52‐dependent manner." (PMID 39401430, 2024). "Overexpression of TPD52 promotes tumor growth in cancer cells, whereas its knockdown reduces cell migration, invasion, and apoptosis." (PMID 39767632, 2024).
cancer (continued). "Significantly, attenuation of the ER stress via depletion of TPD52 facilitated tumorigenesis in a subset of human carcinomas." (PMID 39401430, 2024). "TPD52, initially identified to be overexpressed in many human cancers, was found to form a stable complex with AMPK in cancer cells." (PMID 35666017, 2023). "Studies have reported the role of TPD52 in different cancer signaling pathways, such as PI3K/Akt, PKB, and NFκB, and p21." (PMID 37833790, 2023). "Recent evidence has revealed that tumor protein D52 (TPD52), a regulator of lipid metabolism involved in fatty acid storage and lipid droplet formation, was overexpressed in several cancers, including AML." (PMID 38137407, 2023). "TPD52 is an oncogene located in the amplified region of human chromosome 8q21, and its abnormal expression has been observed in various cancers." (PMID 37564195, 2023). "Knockdown of TPD52 in SK‐BR‐3 cancer cells resulted in increased phosphorylation of AMPKα at Thr172, while the total AMPKα level was not affected." (PMID 35666017, 2023). "To explore the biological effects of TPD52 in cancers, we conducted biochemical and metabolic assays in vitro and in vivo with cancer cells and TPD52 transgenic mice." (PMID 35666017, 2023). "This uneven expression pattern across various cancer types has led to the designation of TPD52 as a “controversial gene”." (PMID 37833790, 2023). "TPD52 exhibits an increased copy number, and is upregulated in a variety of cancers to accelerate tumor formation and progression by affecting cellular survival, proliferation, migration, invasion, and DNA repair." (PMID 37098483, 2023). "The TPD52 gene is located on chromosome 8 at the region frequently amplified in various human cancers." (PMID 37833790, 2023). "As a regulator of lipid metabolism, tumor protein D52 (TPD52) plays crucial roles in the formation of fatty acid storage and lipid droplets, and is a potential biomarker with prognostic value in various cancer types, including AML." (PMID 35957912, 2022). "A previous study reported that TPD52 was a radiation response biomarker in several cancer cell lines." (PMID 36071863, 2022). "Previously, TPD52 expression up-regulation with cancer stage progression was reported in breast cancer." (PMID 35577881, 2022). "Several studies have reported evidence of the role of TPD52 in various signaling pathways of cancers, i.e., in the PI3K/Akt signaling pathway, protein kinase B/Akt signaling pathway, and nuclear factor-κB transactivation." (PMID 35047407, 2021). "Among the family members, TPD52 has been studied the most, due to its role in the malignancy of various cancer cells." (PMID 34217360, 2021). "The novel family member of MAL proteolipid, MAL2, is known to bind with tumor protein D52, thus participating in regulating the tumorigenicity of multiple human cancer types." (PMID 33634966, 2021). "Research about tumor protein D52 (sequences) also elucidates that they are up-regulated in numerous human carcinomas." (PMID 34099820, 2021). "In the low-grade cancer group (grades I and II), the expression of TPD52 was found to be significantly elevated (p < 0.0001) as compared to that in the advance stage (III and IV)." (PMID 33490232, 2020). "Collectively, these data indicated that the upregulation of TPD52 was positively correlated with the poor prognosis in various types of cancer." (PMID 31649118, 2019). "The four-transmembrane protein MAL2 and tumor protein D52 (TPD52) have been shown to be involved in tumorigenesis of various cancers." (PMID 28562687, 2017). "The overexpression of TPD52 was shown in primary carcinoma tissues, lymph node and liver metastasis tissues relative to non-cancerous mucosa tissues, suggesting the correlation between TPD52 and tumorigenesis and metastasis of CRC." (PMID 28562687, 2017).